CASP2 (caspase 2)
Description:
Is a regulator of the cascade of caspases responsible for apoptosis execution. Might function by either activating some proteins required for cell death or inactivating proteins necessary for cell survival. Associates with PIDD1 and CRADD to form the PIDDosome, a complex that activates CASP2 and triggers apoptosis in response to genotoxic stress. [Isoform 1]: Acts as a positive regulator of apoptosis. [Isoform 2]: Acts as a negative regulator of apoptosis. [Isoform 3]: May function as an endogenous apoptosis inhibitor that antagonizes caspase activation and cell death.
Synonyms: CASP-2; NEDD-2; ICH1; NEDD2; PPP1R57; MGC2181; MRT80
Tractability: Small molecule: a drug acting on it is in phase 2 or 3 trials; a structure with a bound ligand is known; a high-quality ligand is known; it has a binding pocket of medium quality; it belongs to a druggable protein family. PROTAC: ubiquitination databases record sites on it; its protein half-life has been measured; a small molecule that binds it is known.
Target class: Cysteine protease; Protease; Cysteine protease CD clan; Enzyme; Cysteine protease C14 family
Gene: Protein-coding gene on chromosome 7 (143,288,215 to 143,307,696, forward strand). Ensembl gene ENSG00000106144.
Subcellular location (Human Protein Atlas): Mitochondria
Pathways (Reactome):
Immune System: NOD1/2 Signaling Pathway
Signal Transduction: NADE modulates death signalling
Gene Ontology:
Molecular function: cysteine-type endopeptidase activity; identical protein binding; protein binding; protein domain specific binding; enzyme binding; cysteine-type peptidase activity
Biological process: cellular response to mechanical stimulus; positive regulation of apoptotic process; protein processing; apoptotic process; apoptotic signaling pathway; DNA damage response; execution phase of apoptosis; extrinsic apoptotic signaling pathway in absence of ligand; intrinsic apoptotic signaling pathway in response to DNA damage; negative regulation of apoptotic process; positive regulation of neuron apoptotic process; luteolysis; neural retina development; protein maturation; proteolysis; regulation of apoptotic process
Cellular component: endopeptidase complex; mitochondrion; cytoplasm; cytosol; nucleolus; nucleus
Genetic constraint (gnomAD): Loss-of-function variants: 37 observed, 51.98 expected, observed/expected ratio (o/e) 0.71, 90% interval 0.55 to 0.94. The upper end of that interval is the gene's LOEUF score, 0.94, which puts it in group 3 of 6, group 1 being the genes least tolerant of losing a copy. Missense variants: 481 observed, 575.98 expected, observed/expected ratio (o/e) 0.84, 90% interval 0.77 to 0.9. Synonymous variants: 203 observed, 215.91 expected, observed/expected ratio (o/e) 0.94, 90% interval 0.84 to 1.06.
Homologues: Orthologues: chimpanzee CASP2 (100% identical), macaque CASP2 (98% identical), rabbit CASP2 (91% identical), dog CASP2 (90% identical), mouse Casp2 (90% identical), rat Casp2 (90% identical), guinea pig CASP2 (88% identical), pig CASP2 (83% identical), tropical clawed frog casp2 (51% identical), zebrafish casp2 (42% identical), Caenorhabditis elegans ced-3 (25% identical), Drosophila melanogaster Dronc (19% identical), and 3 more. Paralogues in human: CASP9 (27% identical), CASP10 (23% identical), CASP8 (21% identical), CASP1 (20% identical), CASP4 (19% identical), CASP5 (19% identical), CASP12 (17% identical), CASP7 (17% identical), CASP3 (16% identical), CASP6 (16% identical), CFLAR (15% identical), CASP14 (15% identical), and 4 more.
Diseases named in the same sentence as CASP2 in open-access papers:
CASP2 is named in the same sentence as 140 diseases in open-access papers, as found by Europe PMC text mining. Sharing a sentence is not in itself a finding about the gene and the disease. The quoted sentences say what the papers report.
breast carcinoma (28 papers, 2013 to 2025). "MMTV/c-neu mammary tumors from caspase-2-deficient animals had a higher proportion of cells with karyomegaly, aneuploidy, and chromosomal aberrations in the form of bizarre mitoses." (PMID 33425918, 2020). "We can summarize that significant caspase-2 activation is associated with apoptosis induction by taxanes in tested breast cancer cells and that caspase-2 is required, at least partially, for the induction as well." (PMID 23672670, 2013). "Moreover, although Casp2−/− mice do not develop tumors spontaneously, loss of Casp2 promotes tumorigenesis in many mouse models including Eμ-Myc lymphoma, c-Neu-driven mammary carcinoma, and ATM−/− lymphoma." (PMID 38676703, 2024). "In B16-F10 (melanoma), LLC1 (Lewis lung carcinoma), MB49 (bladder carcinoma), KPC (pancreatic ductal adenocarcinoma), and 4T1 (mammary carcinoma) cells, caspase-2 was expressed at much lower levels." (PMID 38676703, 2024). "Recently, the overexpression of lncRNA TPT1-AS1 was shown to repress cell proliferation and sensitize breast cancer cells to paclitaxel by elevating caspase-2 levels via the sponging of miR-3156-5p." (PMID 36171196, 2022). "MiR-8073 binds to at least five mRNAs (FOXM1, MBD3, CCND1, KLK10, and CASP2) in various cancers such as colon, pancreatic, and breast cancer in vitro and determines the gene and protein expression levels of these five targets." (PMID 35163589, 2022). "In studies on the cytotoxicity of phytochemicals, attention was paid to the role of caspase-2 in the signaling pathway initiated by DNA damage in liver and breast cancer." (PMID 32993087, 2020). "Using a model of MMTV/c-neu mammary tumor formation, we demonstrated that caspase-2 can also act as a tumor suppressor in the context of an epithelial cancer." (PMID 33425918, 2020). "The involvement of caspase-2 activation in breast cancer cell apoptosis induced by various stimulations has been found." (PMID 27049919, 2016). "We also showed that caspase-2 was significantly involved in taxane-induced cell death in breast cancer cells." (PMID 25685064, 2015). "We can summarize that caspase-2 plays the key role of an apical caspase in main death-inducing pathway after taxane application in tested breast cancer cells." (PMID 25685064, 2015). "In our previous paper we studied the role of caspase-2 in taxane-induced cell death in breast cancer cells." (PMID 25685064, 2015). "In previous study we showed that caspase-2 plays the role of an apical caspase in cell death induction by taxanes in breast cancer cells." (PMID 25685064, 2015). "We showed that the inhibition of caspase-2 expression resulted in decreased activation of caspase-9, -3 and -7 after taxane application in breast cancer cells which implies that caspase-2 plays the role of an apical caspase in these cells." (PMID 25685064, 2015). "A recent study reports Caspase-2 releases from nucleus to cytosol, which is partially required for the apoptosis induction by taxanes in breast cancer cells." (PMID 24997799, 2014). "We demonstrated that caspase-2 is required for apoptosis induction by taxanes in the tested breast cancer cells, probably as an apical caspase." (PMID 23672670, 2013). "We also demonstrated that caspase-2 is required, at least partially, for apoptosis induction by taxanes in both studied breast cancer cell lines." (PMID 23672670, 2013). "In spite of the fact that several studies have shown the involvement of caspase 2 in apoptosis induction by various stimuli in breast cancer cells, the mechanism of caspase-2 involvement in apoptosis induction is not fully understood." (PMID 23672670, 2013). "In our present study, we investigated the role of caspase-2 in apoptosis induction by taxanes in breast cancer cells." (PMID 23672670, 2013). "We have previously found that caspase-2 is significantly activated in breast cancer cells (together with the activation of caspase-3, caspase-9 and caspase-8) following apoptosis induction by taxanes." (PMID 23672670, 2013).
breast carcinoma (continued). "The involvement of caspase-2 activation in apoptosis of breast cancer cells, induced by various stimuli, has also been found." (PMID 23672670, 2013). "Evidence that this is mediated by caspase-2 comes from the finding that stable knockdown of caspase-2 by RNAi abrogates the ability of NRIF3 to induce apoptosis of breast cancer cells." (PMID 23596516, 2013). "Recently, we found that apoptosis was induced by taxane application in SK-BR-3 and MCF-7 breast cancer cells and that caspase-2 was also significantly activated in these cells." (PMID 23672670, 2013). "Caspase-2 is required, at least partially, for apoptosis induction by taxanes in tested breast cancer cells." (PMID 23672670, 2013). "In order to study the role of caspase-2 in apoptosis induction by taxanes in breast cancer cells, we employed a convenient model using SK-BR-3 and MCF-7 cells." (PMID 23672670, 2013). "Moreover, high levels of TRIM16 has been demonstrated to induce apoptosis in human breast cancer and neuroblastoma cells through the induction of caspase-2 activity." (PMID 34452557, 2021). "In addition, evidance that NRIF3/DD1-mediated apoptosis in breast cancer cells involves caspase-2 comes from studes indicating that knockdown of caspase-2 expression transiently by siRNA or stably with shRNA abrogates the apoptotic response." (PMID 25409762, 2014). "Caspase-2 knockout mice develop normally, aside from an increase in oocytes, but when crossed with the Eμ-myc or MMTV/c-neu mouse models, they develop significantly more lymphomas and mammary tumors, respectively, indicating a putative role for caspase-2 as a tumor suppressor." (PMID 24427286, 2014). "We have also shown that the mitochondrial pathway is not, at least in some cases, the predominant pathway of apoptosis induction by taxanes in breast cancer cells, and that caspase-2 may be a major player in this process." (PMID 23672670, 2013). "Interestingly, GSEA of differentially expressed isoforms demonstrated enrichment for genes involved in apoptosis, and thus differential splicing may contribute more broadly than CASP2 to differences in regulation of apoptosis between breast cancer subtypes." (PMID 28263985, 2017). "Thus, there could be a very simple explanation for caspase-2 activation in breast cancer cells after taxane application." (PMID 23672670, 2013). "Thus it is reasonable to assume that caspase-2 could play an important role in apoptosis induction by taxanes in breast cancer cells." (PMID 23672670, 2013). "In contrast, EMT6 (mammary carcinoma), EL4 (T lymphoblast), and Hepa1-6 (hepatoma) feature robust caspase-2 expression, much higher than in Jurkat cells." (PMID 38676703, 2024). "In breast cancer and neuroblastoma cells, it has been confirmed that TRIM16 overexpression induces apoptosis through the induction of caspase-2 activity." (PMID 34452557, 2021). "In breast cancer models, ERβ impairment of DNA damage response involves BRCA1 downregulation and caspase-2 activation which results in mitotic catastrophe and decreased cancer cell survival." (PMID 30992459, 2019). "Apoptotic pathways that ultimately lead to the activation of effector caspases (casp-3, casp-2, and casp- 7) and PARP cleavage have been characterized in breast cancer." (PMID 27861147, 2017). "Although FASTKD2 is only derepressed by NRIF3 in breast cancer cell lines, transiently expressed FASTKD2 leads to caspase-2 dependent apoptosis in other cell types (e.g. HeLa cells)." (PMID 23596516, 2013). "MMTV/c-neu mammary tumors that lacked caspase-2 had a higher mitotic index than caspase-2 wild-type tumors." (PMID 33425918, 2020).
breast carcinoma (continued). "Expression of NRIF3 specifically and rapidly (within 5 h) leads to caspase-2-dependent apoptosis in a wide variety of breast cancer cell lines (Estrogen Receptor positive or negative) but not other cell types." (PMID 23596516, 2013). "Here we have shown that TRIM16 upregulates caspase-2 protein levels in breast cancer and neuroblastoma cells but not non-malignant cells." (PMID 23404198, 2013). "Although results from the mass spectrometry indicated a relatively low caspase-2 mRNA-binding affinity, we chose this candidate because TRIM25 has previously been reported as a key determinant of breast cancer metastasis, suggesting that it could also exert a tumorigenic role in colon carcinoma." (PMID 31842382, 2019). "Surprisingly we found that expression of NRIF3 rapidly leads to caspase-2-dependent apoptosis in a wide variety of Estrogen Receptor positive or negative human breast cancer cell lines (e.g. SKBR3, MCF-7, T-47D, MDA-435, MDA-231 and MDA-231/ER+) and two mouse breast cancer cell lines (4T1 and 67NR)." (PMID 25409762, 2014). "Therefore, we suggest that PIDDosome formation does not represent the main platform for caspase-2 activation in breast cancer cells when apoptosis is induced by taxanes." (PMID 23672670, 2013). "We also reproduced the effect of NEM on the distribution of caspase-2 and FLAG-ERα in studies using T-47D breast cancer cells (not shown)." (PMID 23596516, 2013).
colon carcinoma (20 papers, 2014 to 2026). "As previously demonstrated, the transfection of two different sets of caspase-2-specific siRNA duplexes caused a similar reduction in caspase-2 levels in colon carcinoma cells." (PMID 31842382, 2019). "We report that high caspase-2 expression is associated with lower survival in patients with colon cancer and increased tumor size in HCT116 colon cancer xenografts." (PMID 42208898, 2026). "In summary, SS-a induces apoptosis by facilitating the sequential activation of caspase-4, caspase-2, caspase-8, and caspase-3, thereby inhibiting the proliferation of colon cancer cells." (PMID 41011202, 2025). "The investigation also explored the effect of caspase-4 activation and the activation sequences of caspase-2, caspase-8, and caspase-3 on the apoptosis of human colon cancer LoVo and SW480 cells." (PMID 41011202, 2025). "Previously, we described the fact that the constitutive binding of the E3 ligase TRIM25 to caspase-2 mRNA represses caspase-2 translation in human colon cancer cells, thus leading to an impaired sensitivity towards drug-induced apoptosis." (PMID 36611995, 2023). "It is also important to point out that our results for the first time demonstrated that the caspase-2–Bid axis following AURK inhibition is insufficient to induce apoptosis in certain colon cancer cell lines." (PMID 36621626, 2023). "TRIM25 binds to caspase-2 mRNA and downregulates caspase-2 protein levels to mediate drug insensitivity in colon carcinoma cells." (PMID 36012594, 2022). "In the present study, we unveil a novel mRNA modulatory function of TRIM25, which is critically involved in the negative regulation of caspase-2 in different colon carcinoma cell lines." (PMID 31842382, 2019). "Together, these data demonstrate that transient siRNA-dependent depletion of TRIM25 via increased caspase-2 translation sensitizes colon carcinoma cells to the intrinsic apoptotic pathway." (PMID 31842382, 2019). "In this study, we reported on the identification of TRIM25 as a novel potential regulator of caspase-2 translation in human colon carcinoma cells." (PMID 31842382, 2019). "Consistent with our findings in colon carcinoma cells, earlier studies reported that activation of caspase-2 is critical for an activation of apoptosis in response to doxorubicin or to taxanes." (PMID 31366165, 2019). "Previously, we discovered a cell survival mechanism in colon carcinoma cells by which translation of the pro-apoptotic caspase-2 is constitutively repressed by the ubiquitous mRNA-binding protein, (human antigen R) HuR." (PMID 31842382, 2019). "Functionally, the transient knockdown of HuR significantly increased the sensitivity of colon carcinoma cells to γ-irradiation or drug-induced apoptosis and, importantly, the sensitizing effects were fully rescued after additional silencing of caspase-2." (PMID 31366165, 2019). "Together, our study identified the E3 ligase TRIM25 as a novel caspase-2 RNA-binding protein in colon carcinoma cells, which negatively affects protein expression of caspase-2." (PMID 31842382, 2019). "Using RNA affinity chromatography, we identified the tripartite motif-containing protein 25 (TRIM25) as a bona fide caspase-2 mRNA-binding protein in colon carcinoma cells." (PMID 31842382, 2019). "At first glance, the identification of caspase-2 as a novel target of HuR in colon carcinoma cells simply underscores the broad post-transcriptional cell survival program by HuR." (PMID 31366165, 2019). "Together, these results demonstrate that silencing of TRIM25 expression sensitizes colon carcinoma cells to chemotherapeutic drug-induced intrinsic apoptosis by a mechanism that critically depends on caspase-2." (PMID 31842382, 2019).